ACE (angiotensin I converting enzyme)
Diseases named in the same sentence as ACE in open-access papers (continued):
Sharing a sentence is not in itself a finding about the gene and the disease.
infection (continued). "The infection probably alters the physiological balance between ACE and ACE2, resulting in RAS activation, abnormal vascular endothelial cell functions, and the coagulation system." (PMID 36143443, 2022). "According to these studies, the alterations in the expression of the ACE gene lead to the accumulation of angiotensin, which seem to promote the infection of SARS-CoV-2." (PMID 36430729, 2022). "In particular, the IgG1 antibody was up to 20-fold higher in ACE-overexpressing mice than in WT mice and is an important “first-responder” antibody during infection." (PMID 36016727, 2022). "Patient sera were tested for their ability to inhibit infection of ACE-expressing HEK293 cells by HIV-derived lentiviruses carrying a panel of Spike proteins." (PMID 36497296, 2022). "Chao1/Betta and ACE/Betta indicated reduced richness post-infection with a relatively weak significance for reduced richness in infection samples." (PMID 35915508, 2022). "SARS-CoV-2 entry to host cells is initiated by binding with its receptor, angiotensin-converting enzyme (ACE) 2, and the ACE2 abundance is thought to reflect the susceptibility to infection." (PMID 36613540, 2022). "First, ACE can downregulate ACE2; individuals with the DD genotype would be predicted to have lower ACE2 expression, therefore, less susceptible to infection." (PMID 33390179, 2021). "This renal functional reserve depends on patient’s prior renal function but also on many other factors: hypovolemia induced by prolonged fever, infection-induced digestive disorders, and chronic hypertension, especially if treated by ACE inhibitors." (PMID 33917886, 2021). "It has also very concisely delineated the biochemistry and mechanism of ACE/ACE2 balance in different stages of infection and its role in comorbidity." (PMID 33442728, 2021). "In the first stage- attachment and entry, licorice glycyrrhizin E showed steady binding to S and ACE proteins to inhibit host cells infection." (PMID 33581688, 2021). "The entry and infection strategy of SARS-CoV-2 in a host cell is raised by an amazing way of angiotensin-converting enzyme (ACE) 2 (ACE2) receptor recognition and imbalance of ACE/ACE2 in various organs, especially in the lungs." (PMID 33442728, 2021). "Here it has been discussed the role of interferon and protease during the receptor recognition (begining of infection) and followed by the impact of cytokine and hypoxia in the context of the balance of ACE/ACE2." (PMID 33442728, 2021). "In fact, there are numerous observations that suggest that a dysregulation of the tissue ACE/ACE2 balance during the course of the infection can contribute to the onset of organ damage and hyperinflammatory state." (PMID 34359922, 2021). "In one murine study, selectively reducing ACE expression in neutrophils led to a 6-fold reduction in the clearance of a subcutaneous infection with methicillin-resistant Staphylococcus aureus (MRSA)." (PMID 33042111, 2020). "Human coronavirus NL63 uses the angiotensin-converting enzyme (ACE) 2 receptor for infection of target cells similar to SARS-CoV and has been found to be able to replicate in swine cells in vitro." (PMID 30634419, 2019). "In addition, cell infection by new variants (UK-B.1.1.7, SA-B.1.351, and CA-B.1.429) was prevented by binding of EGCG to viral spike protein 1 adapter protein and ACE cellular receptor sites." (PMID 39925527, 2025). "In addition, these data address the implications of SARS-CoV-2 exposure in the setting of the commonly prescribed ACE-inhibitor, lisinopril, confirming its negligible impact on infection of kidney cells." (PMID 38334329, 2024). "Interaction between ACE-2 and the viral spike protein results in infection." (PMID 38966631, 2024). "This event causes a significant increase in the ACE/ACE2 ratio and, consequently, in the pro-inflammatory pathways, indicating an inflammatory state that could be exacerbated by possible infection." (PMID 36901403, 2023).
infection (continued). "The existence of multiple polymorphisms in the ACE (I/D), ACE2 (rs2074192, rs1978124, rs2074809, rs2074666) genes could explain both the tendency to infection, the expansion to different organs, and the severity of COVID-19 clinical manifestations." (PMID 37308887, 2023). "In addition, as negative regulator of melanization, angiotensin converting enzyme (ACE) was upregulated after SM1 infection." (PMID 36896191, 2023). "Since SARS‐CoV‐2 binds to ACE2 to enter target cells, it has been hypothesized that the widespread use of ACE inhibitors may be to accountable for the infection's high prevalence." (PMID 36324424, 2022). "Whilst simultaneous chemotherapy and ACE inhibition may benefit patients, perioperative conditions and infection may detrimentally alter the immune cell population and protection." (PMID 36016727, 2022). "During bacterial infection, ACE is integral in antigen presentation and in clearing the infection." (PMID 36016727, 2022). "This vicious cycle may then accelerate due to infection-related locally increased ANGII production, which exaggerates ACE/ANGII/AT1R signaling causing systemic failure." (PMID 33435929, 2021). "To date, however, there is no scientific evidence that ACE inhibitors or AT1R blockers increase the risk of infection and adversely affect the course of the disease." (PMID 33925881, 2021). "ACE has become widely known in the past decade as it has been identified as the primary receptor for SARS-CoV and SARS-CoV-2, being closely associated with their infection." (PMID 34768911, 2021). "The lack of medical history at baseline was an additional limitation, recent reports highlighted that some medications, such as angiotensin-converting enzyme (ACE) inhibitors and angiotensin II receptor blockers (ARBs), may facilitate severe infection." (PMID 34555027, 2021). "This suggests that SARS-CoV-2 pathogenicity might be influenced by time of infection due to circadian alterations in the ACE/tACE2 ratio." (PMID 33519802, 2020). "Specifically, the suggestion has been made that ACE inhibitors or ARBs could theoretically contribute to infection via increasing ACE2 receptor expression and hence increase viral load." (PMID 32685191, 2020). "Furthermore, novel SARS-CoV-2 uses an angiotensin-converting enzyme (ACE)-2 in the lungs to enter cells and cause infection." (PMID 32963831, 2020). "The discovery that ACE overexpression enhances both innate and acquired monocytic function holds promise for an entirely new approach for improving the immune response to a variety of stimuli, including infections and tumors." (PMID 27018193, 2016). "However, other proteins are common to both L4 ES and HES, and it is two of these (VAL-1 and ACE-1) that are major antigenic targets in mice rendered fully immune to challenge infection by vaccination with either of these preparations." (PMID 23966853, 2013). "Second, we did not look at several parameters known to influence Hb level and EPO dose, such as residual renal function, adequacy parameters, inflammation/infection, nutritional parameters, treatment with ACE inhibitors, angiotensin II receptor antagonists and level of iPTH." (PMID 19077225, 2008). "Therefore, in the event of contact with the virus, an alteration of the ACE/ACE2 ratio in favor of ACE2 could promote its entry, while in favor of ACE, it could cause more severe symptoms under infection." (PMID 39195662, 2024). "Our association of SNPs in the ACE gene with a clinical score of 4 and this SNP’s higher incidence in males of the oldest age group in our study may confirm the pathophysiologic role of ACE/ACE2 in infection with SARS-CoV-2." (PMID 37971979, 2023). "With roles in antigen presentation and inflammation, the impact of ACE inhibitors must be explored to understand how ACE inhibition may impact our ability to clear infections or malignancy, particularly in the wake of the coronavirus (SARS-CoV2) pandemic and as antibiotic resistance grows." (PMID 36016727, 2022).
infection (continued). "Fifth, the serum levels of ACE, angiotensinogen, angiotensin 1–7, chymase, and the other enzymes of the renin-angiotensin system were not measured in the patients of this cohort, and thus their associations with the risk of infection were not evaluated." (PMID 35155493, 2022). "Patients receiving chemotherapy are especially at risk for hypotension from fluid shifts, infection, etc., and thus anti-hypertensive therapy with ACE inhibitors, ARBs, or BB may not be tolerated." (PMID 34406595, 2021). "Interestingly, it has been shown in mice that SARS-CoV-1 (the coronavirus that caused the SARS epidemic in 2003) infection downregulates ACE2 protein (but not ACE) contributing to severe lung injury." (PMID 33435929, 2021). "However, in retrospective studies no higher risk of infection in patients with ACE inhibitors was found." (PMID 33392206, 2020). "The binding of the virus to ACE-2 cell surface proteins shields it against immune surveillance systems, keeping it attached to the host cell for comparatively longer times, rendering it an effective carrier and prone host for potential infections and further spread." (PMID 32916821, 2020). "Identification of ACE peptide(s) (substrate or product) that elicit an increased immune response may hold great promise for therapeutic manipulation to boost the immune response against a variety of stimuli, including infections and tumors." (PMID 32508938, 2020). "This interaction induces ACE2 downregulation upon infection of alveolar cells, disrupting the renin-angiotensin system (RAS) balance and overactivating the ACE-Ang II axis." (PMID 41012594, 2025). "It is known that ACE2 can counteract the pro-inflammatory pathways activated by ACE, acting as an organ-protective factor, but also acts as a receptor for the entry of SARS-CoV-2 into host cells in case of infection." (PMID 36901403, 2023). "As the receptor for cell entry and infection was identified as ACE2, there has been much debate surrounding the safety of ACE inhibitors during infection." (PMID 36016727, 2022). "Infection with the novel SARS-CoV-2 virus determines downregulation of ACE2 and interrupts the equilibrium between ACE and ACE2 in these organs." (PMID 36145655, 2022). "Twenty-three percent of the participants were on β-blockers, 18% on ACE-inhibitors, 14% on Angiotensin II Receptor Blockers (ARB), and 18% on Aspirin in the period prior to infection." (PMID 34829406, 2021). "An interesting ME/CFS/COVID crossover study used DNA methylation in ME/CFS patients and observed a downregulation of the expression of the human angiotensin-converting enzyme 2 (ACE2) used by the SARS-CoV-2 virus during infection, but not homologous ACE." (PMID 40724879, 2025). "Additionally, we observed significant increases in ACE and ACE2 levels within 60 days post-infection, potentially accounting for the elevated concentrations of their downstream products." (PMID 40725601, 2025). "The angiotensin-converting enzyme 2 (ACE2) provides anchorage for SARS-CoV-2 binding, thus implicating that ACE and ACE2 might contribute to the variability in infection severity." (PMID 39194697, 2024). "Future studies involving selective deletion of Ace in tissue MΦs will further clarify on a potential impact of the Ace pathway on the nonpermissiveness of ACE+ MΦs during persistent STm infection." (PMID 36608122, 2023). "Importantly, amuvatinib inhibited ACE- and TMPRSS2-mediated SARS-CoV-2pp infection in a dose-dependent manner." (PMID 36995225, 2023). "In addition, ACE2, a homologue of ACE, is the recognized receptor for SARS-CoV-2, and infection of cells by SARS-CoV-2 is believed to alter ACE/ACE2 balance." (PMID 37971979, 2023). "Unfortunately, this sample size is not sufficient to assess the impact of pre-infection ACE inhibitor use." (PMID 36589229, 2022).
infection (continued). "The most recent studies tend to support continued use of ACE inhibitors during infection, but, up to now, there was no study that had confirmed the potential benefits of ACE inhibitors for patients with COVID‐19." (PMID 35935270, 2022). "In addition, the main cellular receptor for SARS-CoV2 is ACE, the expression of ACE genes (ACE1 and ACE2), which induce exposure to infection." (PMID 36144690, 2022). "The SARS-CoV-2 virus utilizes angiotensin converting enzyme (ACE-2) for cell entry and infection." (PMID 34201415, 2021). "It is, therefore, possible that ACE-inhibition and ARB usage could beneficially alter ACE2 activity/expression, post infection, particularly in groups that are genetically prone to lower ACE2 activity/expression." (PMID 32501190, 2020). "This lack of impact of ACE inhibitors may be due to a different class of antibodies that a patient produces in response to infection." (PMID 36589229, 2022). "Furthermore, Rhesus macaque ACE has the highest receptor activity for SARS-CoV-2 of 14 mammalian species, and positivity or clearance of infection can be determined based on shedding of virus from nasal secretion, fecal matter, and molecular detection from body tissue after biopsy." (PMID 36143459, 2022). "ACE inhibitors and angiotensin II receptor blockers could lead to changes in the expression of the ACE2 receptor through which the SARS-CoV-2 spike protein may bind cells and hence could affect the likelihood of developing infection following exposure to SARS-CoV-2." (PMID 41012540, 2025). "Similarly, when SARS-CoV-2 infection was analyzed in A549 cells expressing the viral receptor angiotensin-converting enzyme (ACE)-2, anti-nucleocapsid staining at 24.5 h pi indicated a clear reduction in infection efficiency upon miR29b-1*, but not Rand transfections." (PMID 35891387, 2022). "In conclusion, we observed no influence of ACE inhibitors and AT1 antagonists on SARS-CoV-2-induced infection and on SARS-CoV-2-mediated disturbance of cell barrier integrity." (PMID 34440554, 2021). "ACE inhibitors and AT1R antagonist olmesartan did not influence the infection rate of SARS-CoV-2 and were unable to prevent the SARS-CoV-2-induced cell barrier disturbance." (PMID 34440554, 2021). "While analyzing the outcome of infection in cultures of HUVECs (resting state), we found that BK2R did not promote parasite uptake in the absence of ACE inhibitors." (PMID 23355836, 2012). "In the case of vector ACE-GFP replicating in NIH-3T3 cells, the ratio of env to transgene signal begins to increase at infection cycle 9, but does not increase at all in HEK293 or U87-MG cells infected with ACE-GFP, indicating that no major deletion mutants emerge in these cells." (PMID 19203366, 2009). "Thus, regardless of the duration of HCQ use, if an infection is out of control, the suboptimal levels of ACE2 with a remnant virus may aggravate the ACE/ACE2 imbalance." (PMID 35740313, 2022).
heart disease (111 papers, 2005 to 2026). "The DD genotype of the ACE gene has been identified as a risk factor for heart disease in other communities, such as the Caucasus, Australia, and China." (PMID 37193968, 2023). "Conversely, 7 other breeds were less likely to have the ACE gene variant and some of these breeds are also predisposed to cardiac disease (e.g. Boxer, Pomeranian, Miniature Schnauzer)." (PMID 34256860, 2021). "Nearly one-third of dogs in this study were positive for a functionally important ACE gene variant, and for some breeds predisposed to naturally occurring heart disease, the prevalence was much higher." (PMID 34256860, 2021). "This indicates that the suitability of this recruitment to test thehypothesis of the ACE I/D polymorphism was higher in patients withCD and severe forms of cardiac disease with HF." (PMID 32638886, 2020). "By another side, there are reasons for cautioning against a direct effect of ACE on heart diseases risk: ACE polymorphisms are associated with ACE plasma activity, but not angiotensin II plasma levels." (PMID 29268798, 2017). "Although, 97% patients were under treatment with inhibitors of angiotensin-I converting enzyme, this enzyme activity was statistically higher among patients, reflecting the involvement of ACE as risk parameters for heart diseases." (PMID 27894250, 2016). "A previous study showed predispositions for the ACE variant in several breeds known to have genetically‐based heart disease (e.g., Irish Wolfhounds, Cavalier King Charles Spaniels), but there were insufficient numbers of DP in that study to assess breed predisposition." (PMID 36412252, 2023). "The clinical importance of high ACE gene variant-positive prevalence in some breeds requires further study because the highest prevalences were found in breeds that are predisposed to heart disease and therefore may be treated with ACE-inhibitors." (PMID 34256860, 2021). "The clinical importance of high ACE gene variant-positive prevalence in some breeds will require additional studies because some breeds are predisposed to heart disease, for which treatment with ACE-inhibitor medication might be recommended." (PMID 34256860, 2021). "However, we adjusted for diuretics, ACE inhibitors/ARBs, and heart disease in our final models, which are most likely to cause hemodynamic changes, and there was still a significant association between serum chloride and change in eGFR." (PMID 32375681, 2020). "AKI patients were more common in HICs (62.1%) and had higher rates of lung or heart disease and use of beta-blockers, diuretics, angiotensin-converting enzyme (ACE) inhibitors, angiotensin receptor blockers (ARBs), and anticoagulants." (PMID 40004744, 2025). "Together, these data allowed testing of the ACE I/D and AGTR1 polymorphisms as risk factors for susceptibility to Chagas’ heart disease and progression to severe CARD with HFrEF in this population." (PMID 39591456, 2024). "Those with a history of cardiac disease were 3.142 times more likely to die (p = 0.018) while those on ACE inhibitors were 11.764 times less likely to die (p = 0.006)." (PMID 39567199, 2024). "An influence of ACE variant positivity on aldosterone concentrations could have occurred in our study population, because nearly all DP had this variant, which is associated with a higher magnitude of aldosterone breakthrough after ACE inhibition in dogs with heart disease." (PMID 36412252, 2023). "Patients with cardiac diseases are often prescribed beta-blockers, lipid-lowering agents, angiotensin-converting enzyme (ACE)-inhibitors, diuretics and antiarrhythmics to treat their underlying cardiac diseases." (PMID 35725383, 2022). "ACE inhibition and the angiotensin blockade in the form of ACE inhibitors and angiotensin receptor blockers have been proven to be useful in patients with kidney and cardiac diseases." (PMID 35054076, 2022).